PLG (plasminogen)
Diseases named in the same sentence as PLG in open-access papers (continued):
Sharing a sentence is not in itself a finding about the gene and the disease.
gingivitis (1 paper, 2019). A disorder involving inflammation of the gums; may affect surrounding and supporting structures of the teeth. "However, PLG deficiency is known to cause other disorders, such as conjunctivitis of the eye, woody deposits on the gums, and gingivitis, all of which are linked to the inability to clear fibrin." (PMID 31462325, 2019).
glomerular diseases (1 paper, 2025). "There are many experimental studies evaluating the role of urinary plasminogen in glomerular diseases in the literature, but the number of clinical studies is limited, particularly in pediatric patients." (PMID 40576805, 2025). "During glomerular diseases, plasminogen can be filtered aberrantly and pass into the tubular space." (PMID 40576805, 2025).
glomerulonephritis (1 paper, 2022). A renal disorder characterized by damage in the glomeruli. "Therapy with a mutant human PAI-1 (PAI-1R), which connects to the vitronectin matrix but does not inhibit the plasminogen activators, could increase plasmin generation and decrease the matrix accumulation in experimental glomerulonephritis." (PMID 35743361, 2022).
hematoma (1 paper, 2022). A hematoma is a collection of blood from a vascular structure into an extravascular space. "In the group with retrochorial hematoma, there was a negative correlation that was higher between the indicator of the extrinsic coagulation pathway (PT) and plasminogen activity (healthy r = −0.371; p < 0.05, retrochorial hematoma r = −0.539; p < 0.05)." (PMID 36140384, 2022).
hemophilia B (1 paper, 2022). Hemophilia B is a form of hemophilia characterized by spontaneous or prolonged hemorrhages due to factor IX deficiency. "Deficiencies in plasminogen are reportedly linked to cases of splenic rupture, but no such rupture has been linked to hemophilia B." (PMID 36507314, 2022).
hyperthyroidism (1 paper, 2024). Overactivity of the thyroid gland resulting in overproduction of thyroid hormone and increased metabolic rate. "Although a higher percentage of patients with hyperthyroidism had plasminogen values below the reference limit (<75%) compared to euthyroid patients and patients with hypothyroidism, this difference was not statistically significant." (PMID 38541980, 2024). "However, by comparing the mean values of plasminogen, a significantly lower value was found in the group of patients with hyperthyroidism compared to the value in the group of hypothyroid patients and the value in the group of euthyroid participants (p = 0.000)." (PMID 38541980, 2024).
Hypoglycemia (1 paper, 2022). A decreased concentration of glucose in the blood. "By 24-hours, in controls, Protein S continued to show increased %change in response to deep-hypo and vWF continued to show increased %change in mild-hypo; plasminogen emerged at this timepoint as showing increased %change in milder prolonged hypoglycemia." (PMID 36203210, 2022).
inflammatory bowel disease (1 paper, 2024). A spectrum of small and large bowel inflammatory diseases of unknown etiology. "Recently, a first case of colonic involvement in a congenital plasminogen deficient patient with inflammatory bowel disease further supports the role of PLG in inflammation; PLG antigen levels were low." (PMID 38984351, 2024).
intracerebral hemorrhage (1 paper, 2017). A cerebrovascular disorder characterized by bleeding into one or both cerebral hemispheres including the basal ganglia and the cerebral cortex. "The administration of tranexamic acid within 3 hours of iTBI may be a promising treatment; however, the late application of this drug might increase intracerebral hemorrhage by potentiating u-PA-mediated plasminogen activation." (PMID 28826407, 2017).
joint diseases (1 paper, 2024). "No mRNA expression of plasminogen was detected in the synovial tissues from knee joints of either OA or other joint diseases, suggesting that plasminogen translocates into the synovium from circulation." (PMID 38502232, 2024).
liver dysfunction (1 paper, 2023). "In the later stages, plasminogen consumption combined with liver dysfunction leads to low circulating plasminogen levels, which cause fibrinolysis impairment, also defined as fibrinolysis shutdown." (PMID 37569751, 2023).
mastitis (1 paper, 2015). Inflammation of breast tissue during lactation or postpartum due to an obstructed duct or infection. "As an example, the activity of PLG, which is a protease that functions as blood coagulation protein, has also been shown to increase during severe mastitis." (PMID 25693162, 2015).
Menorrhagia (1 paper, 2021). Prolonged and excessive menses at regular intervals in excess of 80 mL or lasting longer than 7 days. "Therefore, we have focused on the use of tranexamic acid (TXA), a drug introduced as early as 1968 for menorrhagia treatment, which works by slowing down the conversion of plasminogen to plasmin, subsequently, reducing fibrinolysis and stabilizing the blood clot." (PMID 33802254, 2021).
microtia (1 paper, 2024). "Then, the following candidate genes ranked in descending order according to their relative impact on the development or severity of microtia: PRKDC > LEPR > PLG > MUC6 > DGKK > GPR161 > WDR36 > BPTF > LRBA > SOD3 > KCNQ4." (PMID 38802922, 2024).
mild cognitive impairment (1 paper, 2022). "Later studies also corroborated these findings and reported a significant upregulation of neuroserpin, alongside plasminogen in the CSF of patients with mild cognitive impairment (MCI), in comparison to subjective cognitive impairment (SCI) subjects." (PMID 35244780, 2022).
mood disorder (1 paper, 2015). A cognitive disorder a disturbance in which the person's mood is hypothesized to be the main underlying feature. "For example, it has been postulated that BDNF affects mood disorders through protein p11 by activating tissue plasminogen activator (tPA)/plasminogen activity, cutting pro-BDNF to increase the production of m-BDNF and leading to an antidepressant effect." (PMID 26091093, 2015). "Therefore, enzymes that influence (tPA)/plasminogen activity are other potential targets to investigate for mood disorders." (PMID 26091093, 2015).
myositis (1 paper, 2018). "In addition, clinical variables such as ASS and ILD, and proteins (plasminogen and thrombospondin) which have previously been linked to myositis were positively correlating with the Jo1+ patients." (PMID 30560888, 2018).
necrotizing enterocolitis (1 paper, 2024). Necrotizing enterocolitis (NEC) is a devastating disease that affects mostly the intestine of premature infants. "Four peptides (αS1-casein, αS1-casein, β-casein and plasminogen) were selected, synthesized and tested against common pathogenic bacteria associated with necrotizing enterocolitis." (PMID 38999788, 2024).
necrotizing fasciitis (1 paper, 2013). "To study streptokinase-dependent and -independent interactions of GAS with the host plasminogen activation system, we used wild-type (WT) GAS strain (5448) isolated from a patient with necrotizing fasciitis and toxic shock syndrome." (PMID 23853591, 2013).
neuroblastoma (1 paper, 2018). Neuroblastoma (NB) is the most common solid, extracranial childhood tumor. "Corroborating this line of evidence, neuroblastoma-derived growth cones secrete tissue plasminogen activator which activates the serine protease plasminogen, which also degrades extracellular matrix." (PMID 30275822, 2018).
nodular goiter (1 paper, 2024). Goiter characterized by discrete tissue mass(es) that may or may not produce thyroid hormones. "Plasminogen (PLG) was reported to show significantly lower expressions in serum samples of PTC patients than the nodular goiter patients." (PMID 38609408, 2024).
nuclear cataract (1 paper, 2021). A cataract (disease) that involves the lens nucleus. "Therefore, the activation of PLG may be the cause of patients with HM suffering from nuclear cataracts." (PMID 33888814, 2021).
osteopetrosis, infantile malignant 2 (1 paper, 2019). "Nevertheless, only CLNC7 (osteopetrosis, infantile malignant 2) and PLG (Plasminogen) genes have been reported associated to hereditary root malformations in humans." (PMID 30573716, 2019).
otitis media (1 paper, 2024). Inflammation of the anatomical structures of the middle ear, which is most often caused by an infectious process. "It is important to note that PLG/D453N has also been associated with otitis media, which has been found to occur spontaneously in PLG-deficient mice." (PMID 38984351, 2024).
peritonitis (1 paper, 2021). Inflammation of the peritoneum (tissue that lines the abdominal wall and covers most of the organs in the abdomen). "In a mouse model of peritonitis, S100A10 is directly involved in inflammation-stimulated plasminogen dependent macrophage recruitment." (PMID 34148033, 2021).
plague (1 paper, 2011). Plague is a severe bacterial infection caused by the gram-negative bacterium Yersinia pestis. "Pla and plasminogen activation are central in plague pathogenesis, and among the omptins, Pla is by far the most efficient plasminogen activator while other omptins either cleave plasminogen poorly or not at all." (PMID 21310089, 2011).
pneumonitis (1 paper, 2013). An inflammatory process affecting the lung parenchyma. "Thus, inhibition of plasminogen fibrinolytic activity protected mice from developing pneumonitis and severe disease." (PMID 23555246, 2013).
Portal vein thrombosis (1 paper, 2023). Thrombosis of the portal vein and/or its tributaries, which include the splenic vein and the superior and inferior mesenteric veins. "Urinary loss of clotting inhibitors, zymogens, and plasminogen; increased hepatic synthesis of fibrinogen and lipoproteins, and hemoconcentration due to fluid loss are some of the factors which predispose NS patients to hypercoagulable states like portal vein thrombosis." (PMID 37229005, 2023).
postpartum hemorrhage (1 paper, 2020). Hemorrhage defined as a blood loss in excess of 500 mL after vaginal delivery or more than 1000 mL after a cesarean delivery. "An antifibrinolytic agent that blocks lysine-binding sites on plasminogen molecules, tranexamic acid reduces bleeding-related mortality in women with postpartum hemorrhage (PPH), especially administered fairly soon after delivery." (PMID 32005192, 2020).
renal dysfunction (1 paper, 2024). "The renal dysfunction causes reduced clearance of urokinase plasminogen activator/soluble urokinase plasminogen activator surface receptor complexes, which results in fibrinolytic activity by converting plasminogen into plasmin." (PMID 39201390, 2024).
respiratory infections (1 paper, 2022). "Interestingly, plasminogen and uPA levels were not altered in COVID‐19 disease but were reduced in non‐COVID‐19 respiratory infections." (PMID 35780481, 2022).
Reye syndrome (1 paper, 2013). An acute and potentially fatal metabolic disorder characterized by cerebral edema, fatty liver and hypoglycemia. "Whether plasminogen-dependent IAV replication contributes to damage of the liver or other extra-pulmonary organs, as observed in Reye's syndrome or other postinfluenza complications requires further investigation." (PMID 23555246, 2013).
sarcoidosis (1 paper, 2023). Sarcoidosis is a multisystemic disorder of unknown cause characterized by the formation of immune granulomas in involved organs. "Higher expression of CD41b, a receptor for fibronectin, fibrinogen, plasminogen, prothrombin, thrombospondin and vitronectin, was reported in IPF patients compared to sarcoidosis and HP BAL samples." (PMID 36835481, 2023).
Sleep apnea (1 paper, 2022). An intermittent cessation of airflow at the mouth and nose during sleep is known as sleep apnea. "This suggests that treatment with CPAP/PAP reduces the hypoxic burden associated with sleep apnea, thereby reducing fibrinolysis, blood coagulation, plasminogen activation, and inflammatory responses." (PMID 35887329, 2022).
squamous cell carcinoma (1 paper, 2022). A carcinoma arising from squamous epithelial cells. "The upregulation of plasminogen activation family members and MMPs has been reported in previous studies using squamous cell carcinomas, including those of the skin." (PMID 35480116, 2022).
staphylococcus aureus infection (1 paper, 2020). An infectious process in which the bacteria Staphylococcus aureus is present. "The expression patterns of proteins involved in the tight junction pathway (related genes: Tuba, PAR6, AMPK, Myosin II, CRB3, JARB, and ZO-3) and Staphylococcus aureus infection pathway (related genes: PLG and KRT1) also show synergistic regulation effects of GA and GKW." (PMID 32765254, 2020).
steatosis (1 paper, 2021). Increased lipid within the cytoplasm of cells. "Four genes had lower expression in steatosis (ABCA1, MTR, MTHFR, and PLG) and five genes had higher expression (SEPHS2, DIO1, HBB, SAA1, and SAA2) in the “selenoprotein micronutrient network” pathway." (PMID 34869521, 2021).
thrombotic microangiopathy (1 paper, 2025). The syndromes of microangiopathic hemolytic anemia, thrombocytopenia, and variable signs of organ impairment, due to platelet aggregation in the microcirculation. "Knowledge gaps exist regarding the role of coagulation pathway mutations such as those in the plasminogen (PLG) gene in the pathogenesis of thrombotic microangiopathy (TMA) and treatment outcomes." (PMID 41169534, 2025). "•Very little is known regarding plasminogen (PLG) mutations in thrombotic microangiopathy (TMA)." (PMID 41169534, 2025).
Trichinella spiralis infection (1 paper, 2019). "The binding and activation of host plasminogen (PLG) by worm surface enolases has been verified to participate in parasite invasion, but the role of this processes during Trichinella spiralis infection has not been clarified." (PMID 31806006, 2019).
trisomy 21 (1 paper, 2025). A chromosomal disorder consisting of the presence of an extra chromosome 21. "Similarly, SERPINA5 and PLG mediate coagulation and fibrinolysis, while GSTM5 participates in oxidative stress defense—mechanisms often disturbed in chromosomal abnormalities and reported in trisomy 21 placentas." (PMID 41614738, 2025).
venous ulcers (1 paper, 2019). "We noted that DVT patients with venous ulcers had higher baseline TAFI activity accompanied by lower α2-antiplasmin compared with the remaining subjects, without any differences in PAI-1 or plasminogen." (PMID 31432450, 2019).
vivax malaria (1 paper, 2017). "Our bioinformatics analysis indicates that blood coagulation and plasminogen activating cascade are the main physiological pathways associated with the differentially abundant serum proteins identified in the vivax malaria patients." (PMID 28667326, 2017).
tumor (227 papers, 1979 to 2025). "The most common type of PLG variants found in tumor samples curated by COSMIC are variants in the protein coding sequence, with missense variants representing 45% of the total." (PMID 38984351, 2024). "These proteins are also present in the surface of certain tumor cells and their over-expression is linked to metastasis, further highlighting the role that the PLG/plasmin system plays in biological processes in which cell migration is required." (PMID 37083884, 2023). "Tetranectin can induce plasminogen activation, which is associated with tumor invasion and metastasis." (PMID 37834257, 2023). "Urokinase plasminogen activator causes the conversion of plasminogen to plasmin, and in the next step, plasmin is suppressed by neuroserpin and serpin B2, and tumor cells pass through the BBB." (PMID 37386445, 2023). "Mmp-19-deficient mice display earlier onset tumor angiogenesis and Mmp-19 reduces endothelial cell angiogenesis by proteolytic cleavage of plasminogen, generating angiostatin-like fragments as endogenous angiogenesis inhibitors." (PMID 35731367, 2022). "Congener 7 reduced vascular formation, along with proliferation and migration, to inhibit tumor growth and possessed plasminogen activation activity, causing a conformational change of plasminogen to dissolve thrombus." (PMID 35736208, 2022). "One study in plasminogen-deficient mice showed reduced tumor growth as compared to mice with plasminogen." (PMID 34066284, 2021). "For example, uPA can activate cell-associated plasminogen, stimulate liver regeneration, and induce arteriogenesis and tumor cell migration in an uPAR-independent manner." (PMID 30241478, 2018). "Evidence from experimental models suggests that cell-associated plasminogen and its activators play a central role in tumor invasion." (PMID 25860938, 2015). "Recently, high levels of activator have been observed to be particularly associated with tumours and transformed cells, and a functional relationship between plasminogen activation and malignancy has been proposed." (PMID 156038, 1979). "Together, the patient tumour and cell line expression data most consistently implicated the plasminogen activation pathway could be important in ALDH1A3‐mediated invasion." (PMID 37753740, 2024). "Notably, plasminogen‐deficient mice (Plg‐) had significantly diminished KPC tumor growth in subcutaneous and orthotopic implantation models." (PMID 37971174, 2024). "Urokinase-type plasminogen activator (PLAU1), which is overexpressed in different human cancer types, encodes a secreted serine protease that converts plasminogen to plasmin; this enzyme can promote tumor cell invasion and metastasis by degrading the components surrounding the extracellular matrix." (PMID 33816223, 2021). "However, unregulated plasminogen activation via the urokinase plasminogen activator (uPA) is implicated in key events in tumour progression, specifically solid tumour invasion and metastasis." (PMID 34439251, 2021). "Among the five genes in ccRCC, ATP6V0D2, DPP6, PADI1 and PLG were significantly associated with AJCC-stage (p < 0.05); ATP6V0D2, C9orf135, DPP6 and PLG were significantly associated with nodal metastasis (p < 0.05); ATP6V0D2, DPP6 and PLG were significantly associated with tumor grade (p < 0.05)." (PMID 32002016, 2020). "High plasminogen expression in tumor cells has been linked to malignancy." (PMID 23894455, 2013). "Finally, using mice genetically deficient in components of the plasminogen activation system, we have previously shown that the anti-tumor activity of the uPA-activated PA in vivo is dependent on cell surface uPA activity." (PMID 21655226, 2011). "The results were consistent with our expectations: CCL5, LOX, and C3 were significantly upregulated in tumor tissues, whereas PLG exhibited markedly higher expression in normal tissues." (PMID 40396123, 2025). "Angiostatin is a 38 kDa proteolytic plasminogen fragment that inhibits angiogenesis in tumour cells." (PMID 40364294, 2025).